SPTAN1 (spectrin alpha, non-erythrocytic 1)
Diseases named in the same sentence as SPTAN1 in open-access papers (continued):
Sharing a sentence is not in itself a finding about the gene and the disease.
tumor (continued). "Thus, the reduction in IL-8 via ERK inhibition represents a potential way to reduce the tumor progression of SPTAN1-reduced-expressing tumors at different levels." (PMID 38891846, 2024). "Similar to Numb gene deletion, CRISPR/Cas9-mediated Sptan1 gene deletion in WT mice did not alter liver size, liver/BW ratios, or liver tumor formation, whereas deletion of Sptan1 in Ww45ΔHep mice remarkably promoted liver enlargement, tumor formation, and YAP activation." (PMID 37843276, 2023). "That said, SPTAN1 may also promote a less favourable tumour biology through its involvement in cell motility and invasion." (PMID 34298848, 2021). "Our transcriptomic pathway analysis indicates that SPTAN1 expression levels may affect tumour aggressiveness and metastatic potential in a context-dependent manner." (PMID 34298848, 2021). "The trend of improved survival in the SPTAN1-high group was maintained after adjusting for patient age and tumour stage in a multivariable proportional hazards model (hazard ratio in the SPTAN1-high group, 0.59; 95% confidence interval, 0.35 to 1.01; p = 0.054)." (PMID 34298848, 2021). "This argues that differential expression of SPTAN1 is particularly relevant in advanced CRC and may be directly linked to tumour aggressiveness and metastatic potential in these patients." (PMID 34298848, 2021). "This is in line with our previously published in vitro data, demonstrating that SPTAN1 knockdown cell lines exhibited weaker cell-cell interactions and may consequently be more likely to detach from the tumour lattice and metastasise." (PMID 34298848, 2021). "On the other hand, knockdown of SPTAN1 in CRC cell lines led to reduced cell-cell contact formation, indicating that tumour cells expressing low levels of SPTAN1 may detach from their primary tumour and metastasise more easily." (PMID 34298848, 2021). "In addition, although alterations in the expression of SPTAN1 have been described in a variety of tumours and tissues, the directionality of these changes (upregulation vs. downregulation) defies any clear classification." (PMID 34298848, 2021). "Indeed, we demonstrate that tumours harbouring a gene expression signature predictive of a favourable response to FOLFOX chemotherapy also exhibit higher SPTAN1 mRNA levels." (PMID 34298848, 2021). "However, both SPTAN1 and APC, which were significantly associated with response, and PARP4, which was mutated in chemosensitive tumours only, have been described as DDR-involved genes." (PMID 34934968, 2021). "It will be interesting to see whether our observations can be validated in a prospective setting, whether they can be replicated in other tumour types, and whether they are generalisable to actin-binding proteins other than SPTAN1." (PMID 34298848, 2021). "Next, the SPTAN1 intensities of tumor tissue and normal mucosa were compared." (PMID 30856214, 2019). "By combining the current knowledge of SPTAN1 in cancer and illustrating potential mechanisms for SPTAN1 influence on tumor development, progression, patient outcome, and therapeutic response, this review aims to summarize existing data about the role of SPTAN1 in carcinogenesis." (PMID 31186638, 2019). "The observed weakened cell-cell contact of SPTAN1 knockdown cells might indicate that tumor cells expressing low levels of SPTAN1 detach from their primary tumor and metastasize more easily." (PMID 30856214, 2019). "Therefore, increase of cytoplasmic SPTAN1 was related to the proliferative and invasive capacity of cells and suggested as a marker for neoplasia." (PMID 31186638, 2019). "Interestingly, when patient outcome and metastasis were correlated with SPTAN1 expression, a decline in SPTAN1 levels was found with increasing tumor stage and metastatic status, which accentuates the divergent role of SPTAN1." (PMID 31186638, 2019).
tumor (continued). "This review summarizes the current knowledge on SPTAN1 in cancer and depicts several mechanisms by which SPTAN1 could impact tumor development and aggressiveness." (PMID 31186638, 2019). "SPTAN1 is a cytoskeletal protein which is involved in cell adhesion and intercellular communication, and the cellular amount of SPTAN1 might have a significant impact on the tumor progression of CRCs." (PMID 30856214, 2019). "The reduced SPTAN1 expression may account for its compromised DNA repair capacity and other tumor promoting properties." (PMID 31186638, 2019). "Regarding the expression of SPTAN1 in other tumor entities, little has been published so far." (PMID 31186638, 2019). "Therefore, physiological SPTAN1 recapitulates several tumor-suppressing characteristics, whereas alteration in regulation and localization can lead to differential tumor promoting effects." (PMID 31186638, 2019). "In the context of tumor aggressiveness, we speculate that high SPTAN1 expression counteracts metastasis by ensuring epithelial cohesion and tight junctional integrity." (PMID 30856214, 2019). "This therapeutic approach might be of special interest for SPTAN1 overexpressing cancers, as SPTAN1 degradation is involved in the canonical pathway and might foster tumor cell death." (PMID 31186638, 2019). "However, there are still many unanswered questions and further investigations are mandatory to better understand the role of SPTAN1 as a potential neoplasia, tumor, and therapeutic response marker." (PMID 31186638, 2019). "The adhesive power imparted by SPTAN1 may promote the formation of strong cell-cell contacts within the primary tumor, thus preventing extravasation and the formation of distant metastases." (PMID 30856214, 2019). "Specifically, we found that MLH1-deficient cell lines exhibit reduced levels of SPTAN1 and have impaired migratory ability, initially suggesting that loss of SPTAN1 may be partly responsible for the reduced metastatic efficiency of MMR-deficient tumour cells." (PMID 34298848, 2021). "Specifically, we asked whether expression of SPTAN1 and actin cytoskeletal genes may be related to tumour purity, and whether the transcripts of interest originate from cancer cells or from immune and stromal cells of the tumour microenvironment (TME)." (PMID 34298848, 2021). "SPTAN1 is comprehensively involved in cell dynamics and a better understanding of its mechanism of action and fine tuning in various processes leads not only to a better understanding of tumor characteristics but also beyond in general cell organization and regulation processes." (PMID 31186638, 2019). "Sun and coworkers could not find differences in SPTAN1 expression by comparing tumor with and without mutations." (PMID 31186638, 2019). "Furthermore, the tumor suppressing properties of SPTAN1 might be regulated throughout the cell and at plasma membranes." (PMID 31186638, 2019). "SPTAN1 might serve as both a tumor suppressor and promotor by several mechanisms." (PMID 31186638, 2019). "Hence, SPTAN1 itself could not only act as a tumor suppressor in the nucleus but also throughout the cell cytoplasm and furthermore stabilize other tumor suppressors." (PMID 31186638, 2019). "In light of a decrease in SPTAN1 expression, we observed in MLH1-deficient tumors and similar to data recently described for the membrane-associated skeletal protein adducin, we propose that SPTAN1 might function two-sided as a tumor suppressor or promotor." (PMID 31186638, 2019). "Therefore, SPTAN1 can have a broad impact on cell dynamics and tumor development." (PMID 31186638, 2019). "Thus, SPTAN1 may serve as a potential biomarker for tumor aggressiveness." (PMID 30856214, 2019). "In order to identify a potential connection between levels of SPTAN1, tumor stage and metastasis of CRCs, we separated our cohort into stages I, II, III and IV CRCs and determined the corresponding SPTAN1 levels." (PMID 30856214, 2019).
tumor (continued). "In 2013, a proteogenomic analysis of human CRC cell lines representing different pathological stages identified SPTAN1 and SPTBN1 as potential markers for tumor and metastases state." (PMID 31186638, 2019). "Due to SPTAN1's multifaceted functions and its role in adhesion and migration, SPTAN1 can influence tumor growth and progression in both positive and negative directions depending on its specific regulation." (PMID 31186638, 2019). "Here, we report that MLH1-deficient CRCs exhibit reduced levels of the cytoskeletal scaffolding protein non-erythroid spectrin αII (SPTAN1), and that tumor progression and metastasis of CRCs correlate with SPTAN1 levels." (PMID 30856214, 2019). "Indeed, our recent analysis of 189 patients with CRC showed that SPTAN1 expression is lower in metastatic compared with non-metastatic tumours." (PMID 34298848, 2021). "SPTAN1's switchboard and transporter function as well as its role in apoptosis, EMT, adhesion, and migration can influence tumor growth and progression in both positive and negative directions depending on the specific regulation." (PMID 31186638, 2019). "Importantly, we show that differential SPTAN1 mRNA levels in our bulk expression data are not influenced by stromal content or immune infiltration of the TME, and therefore likely reflect variations in tumour cell-intrinsic processes." (PMID 34298848, 2021).
cancer (13 papers, 2007 to 2025). A tumor composed of atypical neoplastic, often pleomorphic cells that invade other tissues. "A decrease of SPTAN1 expression induced impaired cellular viability and mobility in all three tested cancer cell lines, underlining the relevance of SPTAN1 for cell growth and migration." (PMID 30856214, 2019). "Notably, HIST1H1D, PSMD2, ANXA2 and SPTAN1 overexpression was associated with elevated protein content in cancer tissues, whereas KRT5 has been rarely observed at the protein level in these tissues." (PMID 32252346, 2020). "The cleavage of SPTAN1 occurs during apoptosis and can be used as a marker of cancer therapeutic efficacy." (PMID 34305593, 2021). "A model established for SPTAN1 in cancer assumed increased apical SPTAN1 as a reaction to pathological stress at the brush border, whereas increased cytoplasmic levels marked neoplastic activity." (PMID 31186638, 2019). "The observed association of MLH1 status with SPTAN1 expression in CRC suggests a predictive value for SPTAN1 as a marker for cancer development and progression." (PMID 31186638, 2019). "The detailed analysis of SPTAN1 is now mandatory to substantiate its relevance and its potential value as a candidate protein for targeted therapy, and as a predictive marker of cancer aggressiveness." (PMID 30856214, 2019). "Studies that have investigated expression and mechanisms of action of SPTAN1 in tumors have allowed gaining some insights into its role in cancer." (PMID 31186638, 2019). "We therefore recommend the determination of SPTAN1 levels in CRCs as a useful marker to predict cancer aggressiveness." (PMID 30856214, 2019). "In particular, SPTAN1 seems to have an important impact on cancer development and progression by various mechanisms." (PMID 31186638, 2019). "Based on the species conservation and minimum free energy (MFE) of their binding sites as well as their cancer/DNA damage response correlations, SPTAN1 was highlighted for further investigation." (PMID 28938540, 2017). "Our findings demonstrate a critical role of the SPTAN1/NUMB axis in cell density sensing, shedding light on the essential role of NUMB isoform splicing in the loss of cell contact inhibition and the initiation of cancer." (PMID 37843276, 2023). "Overexpression of SPTAN1 in cancer was first described in sporadic CRC." (PMID 34305593, 2021). "On one hand, the majority of data suggest overexpression of SPTAN1 in cancer and progression." (PMID 31186638, 2019). "The detection of altered expression of SPTAN1 in tumors indicates that SPTAN1 might be involved in the development and progression of cancer." (PMID 31186638, 2019). "SPTAN1 plays an important role in cancer development and progression." (PMID 31186638, 2019). "In addition, we showed that SPTAN1 has impact on cell viability, mobility and cell-cell contact, and that its expression level correlates with cancer progression." (PMID 30856214, 2019). "Moreover, SPTAN1 cleavage products occur during apoptosis and could serve as markers for the efficacy of cancer therapy." (PMID 31186638, 2019). "Hence, in order to enhance the cytotoxic effects of MMC treatment, it might be reasonable to target SPTAN1 in cancer directly." (PMID 31186638, 2019). "This appears plausible given that the prognostic benefit of high SPTAN1 protein levels was magnified in patients with stage III and IV cancers—the very patients who would typically receive postoperative chemotherapy." (PMID 34298848, 2021). "In our subgroup survival analysis, we saw that the prognostic benefit of high SPTAN1 protein levels was magnified in patients with stage III and IV cancers." (PMID 34298848, 2021).
cancer (continued). "Thus, selective upregulation of NUMB3/4 expression along with a reduction of p-SPTAN1 might be an important mechanism of suppression of MST1/2 activity, leading to loss of cell-cell contact inhibition of cell growth during the initiation and progression of cancer." (PMID 37843276, 2023). "Importantly, NUMB3/4 isoforms that fail to interact with SPTAN1 and activate MST1/2 are predominately upregulated in cancer cells." (PMID 37843276, 2023). "In this regard, the role of SPTAN1 and SPTBN1 in pathologies such as cancer has been reported." (PMID 35563422, 2022). "However, the relationship between miRNAs and SPTAN1 in DNA repair and the potential function by which MMC inhibits cancer cells is poorly understood." (PMID 28938540, 2017). "By disrupting this mechanism, SPTAN1 could have influences on cell detachment, apoptosis, and migration of cancer cells as described for PXN and FAK, both of which are also described to be upregulated in several cancers." (PMID 31186638, 2019). "Whereas SPTBN1 was reduced, SPTAN1 expression was increased in moderately invasive and poorly differentiated CRC compared to nonpolyposis cancer cell lines." (PMID 31186638, 2019).
adenocarcinoma (4 papers, 2015 to 2021). A common cancer characterized by the presence of malignant glandular cells. "For adenocarcinoma specifically, DM was observed in promoters [hypermethylated RASL12; SPTAN1, mir-26a, hypomethylated NQO1, SIRPB1, NF1A] and gene bodies [hypermethylated AKAP13, ANK family, PRKCE, ROS1; hypomethylated FAM171A1, PARK2, BCAS3, RHOJ] and many others." (PMID 26683690, 2015).
neurodevelopmental disorder (4 papers, 2021 to 2023). A behavioral and cognitive disorder with onset during the developmental period that involves impaired or aberrant development of intellectual, motor, or social functions. "We suggest that SPTAN1 is a genetic cause of neurodevelopmental disorders, with 3 phenotypic subgroups." (PMID 36331550, 2023). "We found that SPTAN1 is a genetic cause of neurodevelopmental disorder, which we classified into 3 distinct subgroups." (PMID 36331550, 2023). "Our CoIP/MS analysis suggests that iASPP may directly associate with some proteins that are involved in nervous system development and neurodevelopmental disorders, such as Ank3 and Sptan1." (PMID 37284462, 2023).
peripheral neuropathy (3 papers, 2023). A disorder affecting the peripheral nervous system. "As to mechanism behind the peripheral neuropathy caused by dominant negative SPTAN1 variants, haploinsufficiency caused by nonsense-mediated decay of mRNA encoding mutant alleles has been previously proposed." (PMID 36831804, 2023).
neurological disorders (2 papers, 2022). "In addition, mutations in various members of the spectrin gene family are associated with erythroid cell disorders (SPTA1, SPTB) and neurological disorders (SPTAN1, SPTBN1, SPTBN2, and SPTBN4); however, no human genotype-phenotype correlation has been established for SPTBN5 to date." (PMID 35782384, 2022). "Variants in the spectrin genes SPTAN1, SPTBN1, SPTBN2, and SPTBN4 have been associated with neurological disorders; however, SPTBN5 gene-variants have not been associated with any human disorder." (PMID 35782384, 2022).
SPTAN1 also shares sentences with these, for which no sentence is quoted: breast carcinoma (4 papers); Spastic paraplegia (3); Crohn disease (2); Dystonia (2); epithelial neoplasm (2); hereditary ataxia (2); infantile epileptic encephalopathy (2); Parkinson disease (2); amyloidosis (1); Aphasia (1); behavioral disorders (1); cardiac hypertrophy (1); Cerebellar atrophy (1); ciliopathies (1); colon adenoma (1); COVID-19 (1); distal hereditary motor neuronopathy (1); early infantile epileptic encephalopathy (1); gastric tumors (1); generalized epilepsy (1); glioblastoma (1); glioma (1); head and neck cancer (1); hyperprolinemia type 2 (1); Hypsarrhythmia (1); infection (1); mastitis (1); memory impairment (1); mesothelioma (1); Parkinson's (1).
A further 3 diseases each share a sentence with SPTAN1 in 1 paper.